Y_RNA (Y RNA )
Gene: Miscellaneous RNA gene on chromosome 2 (183,022,859 to 183,022,971, reverse strand). Ensembl gene ENSG00000202141.
Homologues: Orthologues: chimpanzee Y_RNA (97% identical), macaque Y_RNA (96% identical). Paralogues in human: RNY1 (87% identical), RNY1P11 (87% identical), Y_RNA (85% identical), RNY1P10 (84% identical), Y_RNA (84% identical), RNY1P8 (83% identical), Y_RNA (83% identical), RNY1P12 (82% identical), Y_RNA (82% identical), Y_RNA (81% identical), RNY1P15 (80% identical), RNY1P5 (80% identical), and 93 more.